RNU2-48P (RNA, U2 small nuclear 48, pseudogene)
Gene: Small nuclear RNA gene on chromosome 5 (157,976,766 to 157,976,956, reverse strand). Ensembl gene ENSG00000222626.
Homologues: Orthologues: chimpanzee U2 (97% identical), macaque U2 (95% identical), dog U2 (83% identical). Paralogues in human: U2 (89% identical), U2 (86% identical), RNU2-2 (85% identical), RNU2-3P (85% identical), RNU2-6P (84% identical), RNU2-4P (84% identical), RNU2-33P (83% identical), RNU2-14P (83% identical), RNU2-25P (83% identical), RNU2-26P (83% identical), RNU2-52P (83% identical), RNU2-59P (83% identical), and 67 more.